IL10 (interleukin 10)
Diseases named in the same sentence as IL10 in open-access papers (continued):
Sharing a sentence is not in itself a finding about the gene and the disease.
Sepsis (continued). "Elderly patients with chronic critical illness (CCI) and sepsis present increased levels of proinflammatory biomarkers, notably sPDL-1 and IL-10." (PMID 40153575, 2025). "In the context of sepsis immune monitoring, several basal-state biomarkers (i.e. without prior stimulation) are routinely used in clinical practice, such as mHLA-DR, CD4+/CD8+ ratio, and circulating IL-10." (PMID 40796210, 2025). "There appears to be a connection between LOS and IL10 and two uncharacterized genes on chromosomes 16 and 6, and genes involved in NOTCH signaling may be involved in distinguishing sepsis by sex of patient." (PMID 40927580, 2025). "Wehave previously reported high circulating levels of the immunosuppressivecytokines IL-10 and TGF-β in mice during late sepsis and MDSCs from these mice produced copiousamounts of IL-10 and TGF-β upon ex vivo stimulation withbacterial Lipopolysaccharide (LPS)." (PMID 40458301, 2025). "IL-10-producing NK cells have been reported in chronic hepatitis C virus (HCV) infection, viremic HIV infection, chronic hepatitis B virus (HBV) infection, and sepsis." (PMID 40661959, 2025). "In sepsis models involving both standard and multidrug-resistant bacteria, these peptides alleviated tissue pathology by repressing pro-inflammatory mediators (TNF-α, IL-1β) and augmenting anti-inflammatory responses driven by IL-10, TGF-β, and lipoxins." (PMID 41440897, 2025). "The presence of interleukin (IL)‐2, IL‐4, IL‐5, IL‐6, IL‐8, IL‐10, TNF‐α and interferon‐γ was significantly more evident in all three cell culture media transfected with plasma from sepsis patients than in controls, indicating that the transfected cells potentially underwent necroptosis." (PMID 40318009, 2025). "Further, a higher number of IL-10-producing and lower number of TNF-producing CD4+ T cells in PLN substantiate the idea that immunoregulatory surroundings prevail in lymphoid organs after sepsis." (PMID 41142792, 2025). "S100A9protein assembled at IL-10 and TGF-β promoters in MDSCs during late sepsis inmice and humans, and S100A9 could activate a reporter genecontrolled by IL-10 or TGF-β promoter." (PMID 40458301, 2025). "Furthermore, total bile acid, interleukin (IL)-6, and tumor necrosis factor-α concentrations were downregulated after FXR activation, whereas IL-10 concentration was upregulated, indicating the alleviated effect of FXR agonist in sepsis." (PMID 40192065, 2025). "Studies analyzing proinflammatory cytokines, such as IL-8, IL-12, IL-17A, and IL-18, and anti-inflammatory cytokines, such as IL-4, IL-10, and IL-11, have reported no effective neutralizing antibodies to improve the outcomes of human sepsis." (PMID 40136690, 2025). "Since IL-10 and TGF-β play majorroles in sepsis-induced immunosuppression and because S100A9-defficient mice do notgenerate immunosuppressive MDSCs, weasked whether S100A9 protein induces IL-10 and TGF-βexpression in MDSCs during late sepsis." (PMID 40458301, 2025). "Without stimulation, patients in the sepsis cohort had a lower proportion of CD4+ T cells producing IL-10 than did healthy controls." (PMID 39935482, 2025). "In addition, several markers, including Calprotectin, Azurocidin, IL-6, IL-8, IL-10, TNF-α, and IL-35, were progressively elevated from SIRS to Sepsis_A and Sepsis_D cohorts, reflecting disease severity." (PMID 41301767, 2025). "Published evidence the last five years exists for heparin-binding protein (HBP), monocyte distribution width (MDW), interleukin-10 (IL-10), presepsin, procalcitonin and C-reactive protein (CRP) for early sepsis diagnosis; procalcitonin is the most well-studied biomarker for antibiotic guidance." (PMID 40685448, 2025). "Findings highlight that IL-10 levels are higher in patients with septic AKI compared to sepsis patients without AKI, and the receiver operating characteristic curve (ROC) analysis for predicting AKI was nearly as good as NGAL." (PMID 40429966, 2025).
Sepsis (continued). "Furthermore, MDSCs, significantly expanded in sepsis, strongly inhibit effector T cells while relatively promoting Treg differentiation and function by producing Arg1, iNOS, ROS, TGF-β, IL-10 and expressing PD-L1." (PMID 40806563, 2025). "Analysing the gene expression profiles of IL10, PD1, and WT1 in patients who develop sepsis after cardiac surgery may offer critical insights into the mechanisms driving immune dysregulation in this setting." (PMID 41013722, 2025). "In contrast, while sepsis increases serum IL-10, the magnitude of this increase is not circadian-dependent, and this distinct control of pro- and anti-inflammatory cytokines warrants further investigation." (PMID 39968295, 2025). "In sepsis-induced immunosuppression, macrophages exhibit altered cytokine secretion with decreased levels of TNF-α, IL-1β, and IL-12, and increased levels of TGF-β, IL-10, and macrophage migration inhibitory factor (MIF)." (PMID 39372401, 2024). "In a CLP surgery-induced sepsis model of mice, the administration of 5–20 g/kg of the QX1 decoction reduced sepsis-induced upregulated levels of serum IFN-γ, IL-1β, IL-3, IL-6, IL-17, IL-4, IL-10 and TNF-α." (PMID 39051370, 2024). "Other important cytokines in sepsis include IL-6, IL-8, IL-12, IFN-α, G-CSF, and IL-10." (PMID 39252831, 2024). "The stimulation of iNKT cells by α-Galcer did not affect the expression of TGF-β and IL-10 in spleen Treg cells during sepsis, but it decreased their production in liver Treg cells." (PMID 39720538, 2024). "B1a cells are able to secrete IgM as well as immunomodulatory cytokines like IL-10, spontaneously or after infection, and GM-CSF, IL-6, IL-3, TNF; therefore, there is evidence that B1a cells play a protective role in sepsis and survival benefits." (PMID 38474403, 2024). "We found that in neonatal lung, intestine and kidney, where DEL-1 was not suppressed in CS sepsis, a higher IL-10 to IL-17A ratio was observed." (PMID 38263289, 2024). "In support of this regulation, the authors found an inverse correlation between oxPL and IL-10 levels in pediatric patients with defined sepsis but not in critically ill patients without sepsis." (PMID 38649480, 2024). "Therefore, IL-10/DEL-1 axis supports emergency granulopoiesis, prevents neutropenia and promotes sepsis survival in early life." (PMID 38263289, 2024). "Sepsis is a severe clinical syndrome due to the host response to infection, exacerbated by the production of both pro-inflammatory cytokines (TNF-alpha, IL-1-beta>alpha, IL-6, il-8, IL-12, IL-17, COX-2, IRF3) and anti-inflammatory (IL-10) cytokines." (PMID 39768405, 2024). "Based on our results, IL-10-induced DEL-1 is central in promoting emergency granulopoiesis, maintenance of neutrophilia and improving host survival in neonate mice suffering from polymicrobial sepsis." (PMID 38263289, 2024). "During sepsis, dysregulated release of inflammatory cytokines such as tumor necrosis factor-alpha (TNF-α), interleukin-1 beta (IL-1β), interleukin-6 (IL-6), and interleukin-10 (IL-10) can contribute to harmful effects." (PMID 39597952, 2024). "Although satisfactory results have been obtained in animal models for blocking cytokine activity such as TNF-α, IL-17, and IL10, the results in clinical trials on patients with sepsis are not clear." (PMID 38313013, 2024). "When compared to sham-operated mice (sham+vehicle), mice subjected to CLP-sepsis and treated with vehicle (CLP+vehicle) showed a significant increase in the serum levels of pro-inflammatory cytokines IL-1β, IL-6 and anti-inflammatory cytokine IL-10 (P<0.0001)." (PMID 39559354, 2024). "Similar to the case of sepsis, the high concentration of IL-10 observed in the neutrophil environment, does not prevent their preactivation and its negative effects." (PMID 38745328, 2024). "In our study, U. tomentosa did not alter IL-10 levels in a sepsis model, suggesting immunomodulatory activity in infectious diseases." (PMID 38881881, 2024).
Sepsis (continued). "Compared with wild-type mice in CLP sepsis models, mice with FXI knockout had smaller increases in the plasma levels of inflammatory cytokines TNF-α and interleukin-10 (IL-10), delayed responses to the inflammatory cytokines IL-1β and IL-6, and a greater survival advantage." (PMID 38213768, 2024). "Here we demonstrated that immunized mice have higher levels of IL-10 in the peritoneal cavity very early after lethal sepsis challenge compared to nonimmunized mice." (PMID 37681975, 2023). "Our previous study has demonstrated that cystatin derived from helminth Schistosoma japonicum exerted immunomodulatory effects by inhibiting pro-inflammatory cytokines and promoting regulatory cytokines IL-10 and TGF-β and improved the survival rate of sepsis in a mouse model." (PMID 38066526, 2023). "In a recent report, in mice with LPS-induced sepsis, G-Rg6 suppressed TNF-α, IL-6, and IL-1β and increased IL-10, thereby inducing the expression of miR-146a and acting as an anti-inflammatory agent in bone marrow-derived macrophages, which are known to regulate inflammatory responses." (PMID 38202632, 2023). "H3K18la may enhance the overexpression of inflammatory cytokines, including IL-2, IL-5, IL-6, IL-8, IL-10, IL-17, IFN-α, and Arg in patients, and promote the occurrence of macrophage anti-inflammatory response in sepsis." (PMID 36774341, 2023). "Additionally, NaHS treatment in a rabbit model of urinary-derived sepsis showed downregulation of pro-inflammatory markers TNF and NF-kB, and upregulation of anti-inflammatory IL-10." (PMID 36978997, 2023). "Moreover, the ratio of IL10/TNF, a reported indicator of sepsis-induced immunosuppression and sepsis-related mortality, was significantly correlated with the IRG risk score." (PMID 37033939, 2023). "The increase in IL-10 and TFG-ß may indicate that ADSCs activate Tregs by cell contact, increasing circulating levels of Tregs during sepsis." (PMID 38087374, 2023). "Our study showed elevated Foxp3/IL-10 levels and Treg cells in the CNS/periphery by the ITK inhibitor, which may counter the sepsis-mediated depression-like state in mice." (PMID 37175808, 2023). "Our data confirm that glutamine at 10 mM before or after stimulation cannot modulate any induction effect of either LPS or HS on relative HSP90α gene expression, monocyte HSP90α protein, and supernatant IL-1β, IL-6, IL-8, IL-10, and TNF-α concentrations of PBMCs in sepsis." (PMID 36615909, 2023). "Additionally, we demonstrated that IL-10-secreting B cells are present in humans with sepsis-induced ALI, and B cells are the predominant IL-10-producing cells in PMBCs." (PMID 37443161, 2023). "From these data, we conclude that the Gr-1+ leukocytes that protect against polymicrobial sepsis are bona fide MDSCs and hypothesize that the mechanism of MDSC-mediated protection includes abrogation of lethal inflammation by IL-10." (PMID 37681975, 2023). "More than 200 biomarkers of sepsis are described, such as C-reactive protein (CRP), procalcitonin, calprotectin, and some inflammatory cytokines, e.g., tumor necrosis factor (TNF)-α and interleukin (IL)-6, IL-8, IL-10, and IL-12." (PMID 38003758, 2023). "Several biomarkers, although nonspecific, could be used as surrogate markers of the proinflammatory and anti-inflammatory states of sepsis, such as CRP, TREM, TNF-α, IL-6, IL-10 and the TNF/IL-10 ratio." (PMID 37665397, 2023). "Studies also showed that TZDs could increase IL-10 levels, enhance neutrophil recruitment to the infection foci, raise fibroblast growth factor (FGF) 21 levels, and improve survival in animals with sepsis." (PMID 36876083, 2023). "Past studies have also noted the importance of the timing of MSC secretome administration in sepsis, as it plays an important role in determining the positive or negative effects of IL-10." (PMID 37626822, 2023). "The cytokines IL-6, IL-8, IL-10 and TNF-α are established for the assessment of outcome in sepsis." (PMID 37744876, 2023).
Sepsis (continued). "Research findings have consistently demonstrated increased levels of IL-10 in cases of MDR P. aeruginosa-induced sepsis compared to non-MDR P. aeruginosa infection in sepsis patients and in a mouse model of P. aeruginosa pneumonia." (PMID 37624004, 2023). "After LPS induction, supernatant IL-6 (p = 0.005), IL-8 (p = 0.01), IL-10 (p = 0.001), and MCP-1 (p = 0.029) at 24 h and IL-8 (p = 0.015), IL-10 (p < 0.001), and MCP-1 (p < 0.001) at 48 h were higher in SIRS compared to healthy control and/or sepsis." (PMID 36615909, 2023). "Notably, the HLA classifier was significantly positively related to ratios of IL-10/TNF in our study, which implies that the HLA classifier can act as a promising biomarker of sepsis-induced immunoparalysis." (PMID 35685286, 2022). "Most G+ NPMODS sepsis patients experienced significantly higher levels of pro-inflammatory IL-6 without relevant IL-10 elevation." (PMID 36544765, 2022). "The purpose of this study is to determine the diagnostic value and net clinical benefit of interleukin-10 (IL-10), interleukin-17 (IL-17), procalcitonin (PCT), and combination tests in patients with sepsis, which will serve as a standard for sepsis early detection." (PMID 35937269, 2022). "However, HRS given as early as 1 h after LPS-induced sepsis was more effective in decreasing TNF-α and IL-1β expression levels and increasing IL-10 levels compared to other time intervals (p < 0.05)." (PMID 36435787, 2022). "In severe sepsis patients (n = 73), no statistical significance was observed except for IL-10 (p = 0.034)." (PMID 36544765, 2022). "Similar to IL-10-stimulated cells, neutrophils stimulated by LPS or primed by TNF-α in vitro, as well as from the patients with sepsis or NMOSD, also released VEGF, but with a different pattern of chemokines (IL-8, CCL4, CCL5) and cytokines (IL-2, -5, -9, -15, -17, TNF-α) promoting inflammation." (PMID 35757755, 2022). "For G- NPMODS sepsis patients, “IL-6 IL-10 ratio” varied in a narrow range similar to that observed in G- non-NPMODS sepsis." (PMID 36544765, 2022). "The sepsis-induced activation of p38 MAPK was paralleled by a massive increase in the systemic levels of proinflammatory cytokines, such as TNF-α, IL-1β, IL-17 and IL-6, as well as the anti-inflammatory cytokine IL-10." (PMID 35178052, 2022). "It has been previously reported that CQ could protect against liver damage in sepsis-induced acute kidney injury by suppressing the expression of the inflammatory cytokines TNF-α and IL-10 through TLR9 inhibition." (PMID 35346242, 2022). "Furthermore, in septic patients, a high IL-10:TNF ratio equates with the clinical immunoparalytic phase and correlates with poorer sepsis outcomes." (PMID 36264059, 2022). "Blood sPD-L1 may indicate the action of several altered cytokines in sepsis, such as IFN-γ and IL-10." (PMID 35732880, 2022). "While in patients without progressive organ failure, IL-6 and IL-10 levels were still significantly elevated after G- bacterial infection, proving the comparable G+/G- bacteria discriminating power in non-severe sepsis." (PMID 36544765, 2022). "While in the non-bloodstream and non-ARDS group, “IL-6 IL-10 ratio” was higher in G- sepsis patients but without statistical significance." (PMID 36544765, 2022). "Experimental sepsis led to a systemic cytokine storm resulting in the formation of excessive amounts of both pro-inflammatory cytokines (TNF-α, IL-1β, IL-17 and IL-6) and the anti-inflammatory cytokine IL-10." (PMID 35178052, 2022). "Finally, we observed an increase in IL-10 secreting by CD4+ T cells in septic patients, which is consistent with prvious published literature on Tregs in sepsis and septic shock." (PMID 36357845, 2022). "In addition, MSCs were able to reduce the levels of pro-inflammatory cytokines such as IL-1β, IL-6 and TNF-α and elevate the levels of anti-inflammatory cytokines such as IL-10 and TGF-β in the circulation of aged sepsis model rats." (PMID 35197984, 2022).
Sepsis (continued). "In contrast, the levels of almost all the cytokines and chemokines were elevated in the sepsis group compared to the non-sepsis group but it was only the levels of IL-10 that yielded a statistically significant difference." (PMID 35582414, 2022). "In both NPMODS and non-NPMODS subgroups, median levels of IL-6 and IL-10 in patients with G- sepsis were higher than those with G+ sepsis." (PMID 36544765, 2022). "Both IL10 and TGF family proteins have been previously investigated as therapeutic targets in interventional trials, largely due to their measured serum changes in sepsis patients." (PMID 36572854, 2022). "However, in sepsis, bone marrow stromal cells (BMSCs) produce PGE2 to release the anti-inflammatory cytokine IL-10 through EP2 and EP4 receptors on macrophages." (PMID 34116703, 2021). "In addition, serum cytokine levels of IL-1β, IL-6, IL-8, IL-10, IL-12, IL-17A, IL-18, IFN-γ, TNF-α, and calprotectin were found to be elevated in sepsis." (PMID 34654467, 2021). "Understanding the factors that drive the production of IL-10 by NK cells and their impact during dualistic inflammatory states, such as sepsis and other non-controlled inflammatory diseases, is relevant for achieving effective therapeutic advancements." (PMID 35053151, 2021). "Interestingly, while high-dose EPO attenuated serum cytokines in all sepsis models, low-dose EPO reduced only serum TNF-α and IL-10 in BiNx-CLP mice." (PMID 34831360, 2021). "Sepsis resulted in elevation of TNF-α, IL-10, KC, and MCP-1 concentrations in obese mice." (PMID 33859538, 2021). "Interestingly, a feed forward regulation between IL-10 and NGAL has been suggested in another sepsis model, in which NGAL expression correlates with IL-10 level and a better outcome after polymicrobial sepsis." (PMID 34712224, 2021). "This is a point of contention, however, as some researchers argue for a role of TGF-β and IL-10 in modulating NK cell responses in sepsis and trauma, while others report no- or only minimal effects." (PMID 33021569, 2021). "Some laboratory parameters, including serum ferritin, TG, sCD25, IFN-γ, IL-6, IL-10 and TNF-α, could reflect the level of “inflammatory storm, which lead to the “sepsis-like symptoms” and organs injuries in HLH." (PMID 35127776, 2021). "Most patients had elevated IL-10, IL-1Ra, and TNFR-1, which gradually decreased as sepsis resolved." (PMID 34659208, 2021). "Serum IL10 level was systematically higher from D1 to D28 in sepsis than in other groups of patients without IAI, regardless of the primary infection type." (PMID 34795661, 2021). "Murine sepsis studies have yielded contradictory results: Hepatic murine iNKT cells are activated and recruited to the peritoneum upon CLP and produce a wide array of pro-inflammatory cytokines, as well as IL-10." (PMID 33021569, 2021). "In human diseases, the presence of IL-10-producing NK cells has been reported in chronic hepatitis C virus (HCV) infection, viremic human immunodeficiency virus (HIV) infection, chronic hepatitis B virus (HBV) infection, and sepsis." (PMID 35053151, 2021). "Cytokine levels increased in both groups after sepsis onset (wt: IL-6, p = 0.004; TNF-α, p = 0.008; IL-10, p = 0.008; fD−/−: IL-6, p = 0.001; TNF- α, p = 0.002; IL-10, p = 0.001), whereas IL-6 levels were higher in fD−/− mice compared to wild-type at 3-h (p = 0.012) after CLP." (PMID 34396466, 2021). "We also observed that administering IL-38 to mice with CLP-induced sepsis lowered the circulating concentrations of the proinflammatory cytokines IL-1β, IL-6, and TNF-α, while elevating systemic levels of the anti-inflammatory cytokine IL-10." (PMID 34955683, 2021). "Additionally, during sepsis, DCs produce lower levels of pro-inflammatory cytokines (such as IL-12 and TNF-α) and higher levels of anti-inflammatory cytokines (such as IL-10 and TGF-β)." (PMID 34335278, 2021).